TSC2 (TSC complex subunit 2)
Diseases named in the same sentence as TSC2 in open-access papers (continued):
Sharing a sentence is not in itself a finding about the gene and the disease.
angiomyolipoma (continued). "Since the response to mTOR inhibitors in Tsc2+/- mice correlates well with observations in rapamycin kidney angiomyolipoma trials, it would be reasonable to test this dosing strategy in future TSC clinical trials." (PMID 20146790, 2010). "Our findings also clearly demonstrate that the response of kidney tumors to rapamycin in the Tsc2+/- mouse correlates well with observations in early TSC angiomyolipoma clinical trials." (PMID 20146790, 2010). "One possibility is that this individual is a mosaic for the TSC2 748T>C (C244R) susbstitution, and that the angiomyolipoma originates from these mosaic cells." (PMID 18302728, 2008). "We have isolated and characterized a homogenous population of human smooth muscle like-cells (TSC2−/−ASM cells) from an angiomyolipoma obtained from a TSC2 patient after total nephrectomy." (PMID 18958173, 2008). "Conventional PEComas harbor mutations and loss of heterozygosity (LOH) in the TSC2 gene and, more rarely, the TSC1 gene, which may be associated with angiomyolipomas and PEComas." (PMID 37470853, 2023). "mTOR was known to be involved in the pathogenesis of angiomyolipoma (both in syndromic and non-syndromic scenarios), but mutations in genes that regulate this pathway (TSC1, TSC2, and MTOR) were also rarely found in some common renal tumors, such as ChRCC, clear cell RCC, and papillary RCC." (PMID 37845471, 2023). "The age groups, 11–17 (odds ratio [OR], 2.53) and 18–45 years (5.98), TSC2 mutation (1.31), focal seizures (1.50), ADHD (1.47) angiomyolipoma (2.79), and renal cysts (2.63) were significantly associated with a higher risk of facial angiofibroma based on multivariate logistic regression." (PMID 36104799, 2022). "In the multivariate regression, a significantly higher risk of facial angiofibroma was observed for the 11–17 years age group (OR, 2.53), the 18–45 years age group (5.98), TSC2 mutation (1.31), focal seizures (1.50), ADHD (1.47), angiomyolipoma (2.79), and renal cysts (2.63)." (PMID 36104799, 2022). "In a TSC2-null LAM patient-derived angiomyolipoma cell line 621–102, pS6 and peIF4E were co- expressed mainly in the cytoplasm and the immunofluorescent signals could be inhibited by rapamycin (10 nM) plus eFT508 (1 μM)." (PMID 31878201, 2019). "Urotensin-II-induced proliferation and migration were reproduced in TSC2-deficient human angiomyolipoma cells, but not in those stably expressing TSC2." (PMID 27458154, 2016). "We found small mutations in TSC2 in 7 of 8 angiomyolipoma that were sequenced, and the single case that did not harbor a mutation was the VHL patient." (PMID 21949787, 2011). "We previously isolated, from an angiomyolipoma of a TSC2 patient, a homogenous population of smooth muscle-like cells (TSC2−/− ASM cells) that have a mutation in the TSC2 gene as well as TSC2 loss of heterozygosity (LOH) and consequently, do not produce the TSC2 gene product, tuberin." (PMID 18958173, 2008). "The Tsc2+/- mouse is a useful model for the kidney angiomyolipomas that develop in TSC." (PMID 17986349, 2007). "The diagnosis of TSC2/PKD1-CGS is often based on the typical appearance of renal cysts (diameter exceeding 2 cm at an early stage) and variable coexistence with angiomyolipoma." (PMID 36979978, 2023). "In general, TSC2 disease was more severe than TSC1, with more subependymal giant cell astrocytomas and angiomyolipomas, higher incidence of pharmacoresistant epileptic seizures, and more severe neuropsychiatric disorders." (PMID 29196670, 2017). "These cells were derived from the angiomyolipoma of a woman with the sporadic form of LAM and carry bi-allelic inactivation of the TSC2 gene." (PMID 23555865, 2013). "Thus all 13 sporadic angiomyolipoma and LAM specimens showed evidence of biallelic TSC2 inactivation." (PMID 27494029, 2016).
angiomyolipoma (continued). "Concurrent analysis of angiomyolipomas and LAM lung samples from women with sporadic LAM but not TSC has demonstrated that these two lesions have identical point mutations in TSC2, providing strong evidence that they are clonal and derived from a common cell." (PMID 27494029, 2016). "Tuberin (TSC2) was weak or absent in angiomyolipomas, but present in healthy kidney, whereas, phosphorylated p70 S6 kinase and pS6 were present only in angiomyolipomas." (PMID 22765013, 2012). "Individual I:1 tested negative for the TSC2 748T>C (C244R) substitution, but was diagnosed with angiomyolipomas." (PMID 18302728, 2008). "Despite extensive characterization of the TSC2 pathway in the regulation of mTOR and other downstream signals, the molecular mechanisms that link the biochemical pathway that involve in developing cell fibrosis in TSC patients with angiomyolipoma remain poorly understood." (PMID 25149531, 2014).
autism (58 papers, 2010 to 2025). Persistent deficits in social interaction and communication and interaction as well as a markedly restricted repertoire of activity and interest as well as repetitive patterns of behavior. "In animal models of tuberous sclerosis (Tsc2+/−), one of the variants of syndromic autism, it has been shown that the regulation of the mitochondrial life cycle through autophagy, or mitophagy, is critically impaired both in the axon and throughout the body." (PMID 41155356, 2025). "In a mouse model with heterozygous mutants of tuberous sclerosis complex 2 (TSC2), which is a cause of tuberous sclerosis manifesting with seizures, autism, and cognitive deficits, a global reduction of histone H3 acetylation was found in hippocampus tissues." (PMID 39563472, 2024). "Between 30% and 60% of people who harbor loss-of-function mutations in the TSC1 and TSC2 genes receive an autism diagnosis, with mutations in the TSC2 gene showing a higher risk." (PMID 39262819, 2024). "Mutations in the TSC1/TSC2 genes lead to the overactivation of mTOR signalling, which is also linked to nonsyndromic autism." (PMID 34576223, 2021). "Complete loss of TSC1 or TSC2 leads to excessive mTOR activity, and mutations in other components of the mTOR pathway are also linked to autism in humans such as PTEN, RHEB, and MTOR." (PMID 33054857, 2020). "Overall, 73.2% of patients carried TSC2 genetic variant and, among patients with TSC and autism, the percentage of TSC2 individuals was 85.6%." (PMID 32849171, 2020). "The mTOR inhibitor rapamycin has rescued not only the synaptic plasticity but also the behavioral deficits in adult mice with syndromic autism, a heterozygous, inactivating mutation in the TSC2 gene." (PMID 31847491, 2019). "An ASD study that identified rare variants in mGLUR signaling pathway reported rare and deleterious variants in the SHANK3, TSC1, and TSC2 genes in non-syndromic autism individuals." (PMID 31744938, 2019). "Pharmacological treatments based on inhibition of this pathway have been developed and tested in mouse models for Fragile X syndrome, eIF4E dysregulation, and TSC1 and TSC2, with amelioration of autism-associated deficits in all cases." (PMID 31548888, 2019). "TSC2 is directly involved in regulating mTORC1 downstream of AKT, and autism-linked mutations in TSC2 cause increased mTOR activation and a de-coupling of mTOR from AKT." (PMID 30237867, 2018). "For example, haploinsufficiency of Shank3, CMIP, FOXP2 and Tsc2 has already been linked to the etiology and phenotypic characteristics of autism." (PMID 23451085, 2013). "Whereas mutations in the TSC1 and TSC2 genes typically cause syndromic autism in the context of TSC, our results suggest that these genes contribute to non-syndromic autism risk independent of their causal role in TSC." (PMID 22558107, 2012). "Likewise, mutation of Tuberous Sclerosis Complex 2 (TSC2), a further autism risk gene, changes spine morphologies and glutamatergic transmission and points at a link between MET and TSC signaling and compromised neuronal connectivity in ASD." (PMID 34054427, 2021). "Given the central role of mTOR for the stabilization of inhibitory synapses dependent on Met signaling, it is conceivable that Tsc2, another autism risk gene and negative regulator of mTOR, might also be involved in gephyrin clustering." (PMID 34054427, 2021). "It remains essential to examine the functional impact of the missense variants detected in idiopathic ASD to conclude as to whether rare functional variants in TSC1/TSC2 could be a very rare cause of non-syndromic autism." (PMID 23514105, 2013). "A damaging de novo mutation R1580W has been identified in the GAP-domain of TSC2 in one of the recent autism exome sequencing studies raising the question as to whether a subclinical TSC was present in that patient." (PMID 23514105, 2013). "Mutations in the TSC genes, TSC1 and TSC2 are known to cause syndromic autism." (PMID 23514105, 2013).
autism (continued). "Causal roles for TSC1 and TSC2 have previously been demonstrated in syndromic autism." (PMID 22558107, 2012). "In literature, several autism models with mutations in Foxp2, Nlgn4, and Tsc2 exhibit reduced USV." (PMID 21203536, 2010). "As early as 2008, it was first shown that adult Tsc2+/− mice, one of the most common syndromic autism animal models, practically overcame both behavioral deficits and learning problems after a short course of rapamycin." (PMID 41155356, 2025). "The reduced vocal repertoire and simpler, fixed call sequences were also seen in other schizophrenia/ autism models, such as Poly(I:C) rats or TSC2 heterozygous mice." (PMID 40721614, 2025). "Tuberous sclerosis complex (TSC) is a rare monogenic disorder co-diagnosed with high rates of autism and is caused by loss of function mutations in the TSC1 or TSC2 genes." (PMID 37293130, 2023). "An example of an autosomal dominant genetic disorder associated with an increased risk of developing autism, for which there are potentially effective treatment options, is tuberous sclerosis, which is caused by defects of the TSC1 or TSC2 genes." (PMID 36980949, 2023). "A hyperactive mTOR pathway, as a result of Tsc2 insufficiency, is probably responsible for the autism-related symptoms in TSC." (PMID 34576223, 2021). "Gene defects associated with upstream regulators of mTOR (TSC1, TSC2, and PTEN), are associated with autism and in many cases, macrocephaly." (PMID 31024350, 2019). "The most direct evidence comes from monogenic, syndromic forms of autism, many of which are caused by lost or reduced function in genes, including eIF4E, FMR1, PTEN, NF1, TSC1, TSC2 and PRKCB1, that negatively regulate the pathway or its subsystems." (PMID 31548888, 2019). "Several genes that often occur in minority polymorphisms in autism (FMR1, Tuberous Sclerosis complex 1 and 2 -TSC1, TSC2, and phosphatase and tensin homolog-PTEN) and the STEP protein that is upregulated in FXS65 are associated with these pathways." (PMID 27212113, 2016). "Two recent studies looked at the possible role of TSC1 and TSC2 genes along with others in non-syndromic autism." (PMID 23514105, 2013). "Although some of the genes studied are known to cause syndromic ASD (e.g. FMR1, TSC1, TSC2, UBE3A), their possible role in non-syndromic autism has been unclear." (PMID 22558107, 2012). "The over-representation of rare, potentially disruptive variants in genes previously implicated in ASD (TSC1, TSC2, SHANK3) provides validation of this approach to detect genes that contribute genetic risk in autism." (PMID 22558107, 2012). "Loss of function in multiple genes that negatively regulate mTOR, including TSC1, TSC2, PTEN, NF1, and FMR1, has been linked to syndromic autism with increased head size and high rates of seizures; both of these traits are also found in mice heterozygous for AMBRA1 loss of function." (PMID 31687209, 2019). "Although the manifestations of TSC include ASD in up to 50% of cases, our findings additionally implicate TSC1 and TSC2 as risk genes for non-syndromic autism independent of their causative role in TSC." (PMID 22558107, 2012). "Although significant enrichment of rare, potentially disruptive variants in AGRE samples relative to controls was limited to the TSC1, TSC2, SHANK3, and HOMER1 genes, individual variants in additional genes suggest a role for the Ras/ERK cascade in autism susceptibility." (PMID 22558107, 2012).
autism (continued). "Higher burdens of rare, potentially deleterious variants were identified in autism cases for three pathway genes previously implicated in syndromic autism spectrum disorder, TSC1, TSC2, and SHANK3, suggesting that genetic variation in these genes also contributes to risk for non-syndromic autism." (PMID 22558107, 2012). "Autism‐like features could be observed in 2–4 months old, heterozygous Tsc2+/− animals." (PMID 39192595, 2024). "In addition, pharmacological intervention with SAHA also restored the histone H3 acetylation level, reversed pathological form of synaptic plasticity, and abrogated the epileptic phenotype in the TSC2+/− mice showing the neurological manifestations including seizures, autism and cognitive deficits." (PMID 39563472, 2024). "Moreover, it was shown that inhibition of mTOR improves ASD-like behaviours related to Tsc2 or Tsc1 haploinsufficiency (in several Tsc1+/− or Tsc2+/− animal models), pointing to mTOR attenuation as an effective strategy in various mTOR-related brain dysfunctions, including autism." (PMID 37108467, 2023). "In the experiments, the authors used TSC2 +/−/Poly (I: C) model mice to simulate seasonal viral infections, and statistical analysis of the human TSC population revealed an association between high seasonal influenza activity in late pregnancy and the onset of autism in the child in addition to TSC." (PMID 35055151, 2022). "Since mounting evidence has established autism as a disorder of the synapses, we tested whether rare genetic variants in TSC1, TSC2, MYCBP2, RHEB and FBXO45, genes that regulate mTORC1 signaling and/or play a role in synapse development and function, contribute to the pathogenesis of idiopathic ASD." (PMID 23514105, 2013). "Other candidate genes of autism include NF1, PTEN, MET, TSC1, TSC2, and CYFIP1, that are located in the duplication region (15q11–13)." (PMID 31744938, 2019). "However, another study seeking to determine whether TSC2 variants contribute to nonsyndromic autism risk did not see an increased frequency of TSC2 variants in ASD probands from a cohort of 300 individuals from the Simons Simplex Collection (SSC)." (PMID 29271092, 2018). "Indeed, a recent preclinical study of adult rats with TSC2 mutations and developmental status epilepticus, and a case study of a patient with TSC both reported improvements in social deficit behaviors, including autism-related behaviors, following mTOR inhibitor therapy with everolimus." (PMID 28288694, 2017). "At the level of individual pathway genes, we identified a significant excess of SNVs in the autism population for the TSC1, TSC2, SHANK3, and HOMER1 genes (P<0.05)." (PMID 22558107, 2012). "A recent study also identified a number of SNVs in the TSC1, TSC2, and SHANK3 genes in simplex autism cases (although the frequency of SNVs in these genes in controls was not reported)." (PMID 22558107, 2012). "Molecular changes may also influence the expression of genes involved in autism symptoms and genetic syndromes such as GABRB3, FMR1, TSC1 and TSC2." (PMID 29340132, 2018). "Interestingly, our analysis revealed a significant excess of rare, potentially deleterious variants in three known autism genes, SHANK3, TSC1, and TSC2, in individuals with non-syndromic autism." (PMID 22558107, 2012).
lymphangioleiomyomatosis (54 papers, 2009 to 2025). A multifocal neoplasm with perivascular epithelioid cell differentiation affecting almost exclusively females of child-bearing age. "Mutations in TSC1 and TSC2 genes located on chromosomes 9 and 16 have been identified in patients with lymphangioleiomyomatosis." (PMID 41383536, 2025). "The combination of RES and rapamycin has been successful in studies on bladder and breast cancer cell lines, lymphangioleiomyomatosis cells, TSC2-deficient cell lines, and TSC2-deficient xenograft tumors in mice." (PMID 40077707, 2025). "Lymphangioleiomyomatosis (LAM) mutations in TSC1 or TSC2 genes result in the activation of the mTOR complex 1 (mTORC1)." (PMID 33922083, 2021). "Lymphangioleiomyomatosis (LAM) is a rare fatal cystic lung disease due to bi-allelic inactivating mutations in tuberous sclerosis complex (TSC1/TSC2) genes coding for suppressors of the mechanistic target of rapamycin complex 1 (mTORC1)." (PMID 33159078, 2020). "Lymphangioleiomyomatosis (LAM) is a devastating lung disease caused by inactivating gene mutations in either TSC1 or TSC2 that result in hyperactivation of the mechanistic target of rapamycin complex 1 (mTORC1)." (PMID 32078667, 2020). "Tuberous Sclerosis Complex (TSC) and Lymphangioleiomyomatosis (LAM) are caused by inactivating mutations in TSC1 or TSC2, leading to mTORC1 hyperactivation." (PMID 30816188, 2019). "show in TSC1- or TSC2-deficient lymphangioleiomyomatosis patient derived cells that BI2536 moderately inhibits autophagy." (PMID 28102733, 2017). "TSC2 mutations are also the underlying cause of lymphangioleiomyomatosis (LAM), a proliferative disorder that almost exclusively affects women and results in cystic destruction of the lungs." (PMID 19593385, 2009). "Furthermore, patients with the genetic disorder tuberous sclerosis complex (TSC) (mutations in the TSC1 or TSC2 gene), commonly develop tumors like astrocytomas or angiomyolipomas as well as the related lung disorder Lymphangioleiomyomatosis (LAM)." (PMID 30764584, 2019). "Lymphangioleiomyomatosis/TSC cells bear a TSC2 germline mutation on exon 21 (R750X-2251 C>T)." (PMID 24606538, 2014). "The team developed a lung-targeted LNP to specifically deliver mRNA that encoded the normal Tsc2 gene into Tsc2-deficient TTJ cells for the treatment of lymphangioleiomyomatosis (LAM) caused by mutations in the Tsc2 gene." (PMID 36559175, 2022). "Lymphangioleiomyomatosis (LAM) is a rare cystic lung disease primarily affecting women, driven by TSC1 or TSC2 mutations that lead to constitutive mTORC1 activation and progressive respiratory failure." (PMID 41180734, 2025). "Although rapalog therapy causes tumor reduction in lymphangioleiomyomatosis (LAM) and angiomyolipoma (AML), each due predominantly to inactivating TSC2 mutations, there was a dramatic tumor regrowth after treatment cessation." (PMID 41277553, 2025). "In recent years, monogenic causes of cystic lung disease have been successively deciphered: Lymphangioleiomyomatosis (LAM) is associated with variants in tuberous sclerosis complex (TSC) 1 and TSC2 genes and sporadic LAMs often display somatic mosaicism." (PMID 40432300, 2025). "Similarly, patients with a progressive lung disease, lymphangioleiomyomatosis (LAM), can have sporadic LAM (S-LAM) with TSC1/TSC2 variants, probably two somatic hits, isolated to the affected tissue." (PMID 38540392, 2024). "In contrast, a recent publication reported that renal tumors, lymphangioleiomyomatosis, and kidneys from TSC2 heterozygous mice display increased lysosomal biogenesis that occurs due to hypo-phosphorylation and nuclear translocation of TFEB." (PMID 34685691, 2021). "This study is to investigate the effects of zoledronic acid (ZA) on TSC2-null cell proliferation and on the tumor progression and recurrence in mouse models of lymphangioleiomyomatosis (LAM)." (PMID 32063747, 2020).